IL1A (interleukin 1 alpha)
Diseases named in the same sentence as IL1A in open-access papers (continued):
Sharing a sentence is not in itself a finding about the gene and the disease.
tumor (continued). "Co-culture studies on human melanocytic cells showed that IL-1α and IL-1 β exhibit autocrine behavior by stimulating tumor cells themselves to invade and proliferate, or exert paracrine effects on stromal cells in the microenvironment." (PMID 23847622, 2013). "As tumors outgrow their vascular supply, necrosis takes place and here the source of the IL-1α precursor is the tumor itself." (PMID 24312098, 2013). "IL1α/β and TNFα secreted by the tumor cells are common paracrine activators of CAFs induced inflammation in a variety of cancers and experimental models." (PMID 23630584, 2013). "Very little is known about interactions between IL-1α and IL-1β expressed at tumor sites by either the malignant or microenvironment cells." (PMID 23847618, 2013). "The expression of IL-1α by PDAC affects the tumor cell function, making them more prone to migrate as neutralizing of IL-1α with IL-1RA decreased the migratory capacity." (PMID 23951028, 2013). "The paracrine action of IL-1α, expressed by the tumor cells, seems to be important in the case for developing PDAC." (PMID 23951028, 2013). "Immunosuppression induced by IL-1β in the tumor microenvironment, mainly through MDSC induction, usually inhibits or masks anti-tumor cell immunity induced by cell-associated IL-1α." (PMID 23847618, 2013). "These immune cells release pro-inflammatory molecules, such as TNF-α, IL-6, and IL-1α, which activate signaling pathways and promote tumor growth." (PMID 23272179, 2012). "The 3-methylcholatrene-induced tumor incidence was reduced in IL-1α knockout mice, but increased in IL-1Ra mice with concomitant maturation of NK cells and anti-tumor immunity." (PMID 22567084, 2012). "In those studies, cancer-derived IL-1a played a key role in inducing CAFs to release factors with functions in tumor migration and invasion (i.e., IL-1a, IL-8, IL-6, and others)." (PMID 23342263, 2012). "IL-1α tumor suppressor characteristics have been further confirmed in vivo where IL-1α produced by tumorigenic fibroblasts decreased the number of tumor growths, as well as increased tumor rejection by facilitating activation and expansion of helper T cells." (PMID 21765834, 2011). "When released in its precursor form, such as from necrotic tumor cells under hypoxic conditions commonly seen in OC, IL-1α can promote an inflammatory response perpetuating the chronic inflammation associated with the onset of disease." (PMID 21765834, 2011). "IL-1α has tumor suppressor functions that should be further investigated in OC; however, the effectiveness of IL-1α as a treatment option is likely limited to early onset of disease." (PMID 21765834, 2011). "HBD-3 stimulated the expression of tumor-promoting cytokines, including interleukin-1α (IL-1α), IL-6, IL-8, CCL18, and tumor necrosis factor-α (TNF-α) in macrophages derived from human peripheral blood monocytes." (PMID 20544025, 2010). "Tumour-associated macrophages cultured with M-CSF, TNF-α and IL-1α also showed formation of TRAP+ and VNR+ multinucleated cells." (PMID 16641914, 2006). "Results of IL-1α or IL-1β mRNA expression in several tumor cell lines evaluated by quantitative RT-PCR." (PMID 17096856, 2006). "Induction of NOS II in HT-29 cells by the cytokines IFN-γ (100 U ml−1) and IL-1α (1 ng ml−1) and production of NO by the tumour cells itself significantly increased Matrigel® invasion of HT-29 cells about 75%." (PMID 11953890, 2002). "Calculation of the overall survival rates showed a decreased overall survival time for patients with low levels of IL-1α mRNA in their tumours (log rank; P = 0.0002, median follow up: 37 months)." (PMID 11161396, 2001). "Low tumoral IL-1α expression predicted decreased survival of patients with poorly differentiated tumours (P< 0.005) and of patients with invasive tumours (P = 0.02)." (PMID 11161396, 2001).
tumor (continued). "In the present studies the effect of bilateral adrenalectomy on the pathophysiologic responses to recombinant human interleukin-1 alpha (rHIL-1 alpha) was determined in RIF-1 tumour models." (PMID 2297494, 1990). "Together this work suggests that increased tumor IL-1α expression triggers a shift toward an oxidative and ferroptotic environment, leading to an aggressive tumor phenotype and drug resistance; but also reveals a unique vulnerability to agents that induce ferroptosis." (PMID 42013543, 2026). "It has also been shown that both IL-1α and IL-1β may help with tumor angiogenesis and invasiveness as PCa develops, as stated in a review by Ullah, Jiao, and Shen." (PMID 40427694, 2025). "Furthermore, we identified a significant increase in interleukins and tumour necrosis factors, including IL‐1a, IL‐1b, IL‐6, IL‐17C, IL‐32, IL‐36G and TNF, along with its associated enzyme." (PMID 39865778, 2025). "However, immune inflammatory cells are capable of tumor promotion (IL-1a release) by enhancing cell proliferation and angiogenesis." (PMID 41375025, 2025). "The role of IL1A in the tumor microenvironment is notably intricate." (PMID 40612864, 2025). "Our findings suggest that IL1A may promote neutrophil migration, potentially enhancing the infiltration of antineoplastic neutrophils and inhibiting the recruitment of pro-tumor neutrophils in KIRC therapy." (PMID 40612864, 2025). "Moreover, co-culture experiments indicated that IL-1α can enhance stromal activation and inflammatory cytokine production, reinforcing a tumor-promoting microenvironment." (PMID 40940885, 2025). "Additionally, we acknowledge that other TAM-mediated, tumor-supportive mechanisms are most likely contributing to T-cell dysfunction, beyond IL-1α and PGE2 activity." (PMID 40176808, 2025). "In contrast, IL-1α may primarily function as a suppressor in malignant cells by recruiting immunocompetent cells to the tumor microenvironment and stimulating an immune response to combat the tumor growth." (PMID 40535773, 2025). "The role of IL-1α in tumor biology is complex, but many studies suggest it has pro-tumor activity." (PMID 40176808, 2025). "IL‐1α also stimulates paracrine senescence in adjacent cancer cells to prompt tumor suppression." (PMID 39811803, 2025). "When overstimulated, however, this pathway stimulates proliferation of tumor cells via nuclear factor NF‐κB/JNK/ERK signaling, thereby inducing the production of cytokines, such as TNF, IL‐1α, and IL‐6, which act in a positive feedback loop to promote tumor growth." (PMID 40922674, 2025). "More recent studies suggest that IL-1α can also be activated by sublethal damage, such as oxidative stress and DNA injury, and plays roles in both tumor progression and anti-tumor immunity within the tumor microenvironment." (PMID 40940885, 2025). "Inflammatory cytokines, including IL-1α, IL-3, IL-9, and IL-12, are pivotal in amplifying the immune response, particularly in immune surveillance and the clearance of tumor cells, by facilitating the proliferation, differentiation, and activation of immune cells." (PMID 40426998, 2025). "Interleukin-1 alpha (IL-1α) expression initiates a cascade leading to a proinflammatory state that activates nuclear factor-kappa-B (NF-κB) and promotes epithelial–mesenchymal transition, thereby facilitating tumor metastasis." (PMID 40041912, 2025). "Targeting IL-1α signaling—via neutralizing antibodies or pathway inhibitors—could simultaneously modulate tumor cells and stromal fibroblasts, disrupting the inflammatory crosstalk that drives OSCC progression." (PMID 40940885, 2025). "Interleukin-1 alpha (IL-1α) is a pro-inflammatory cytokine, which have been studied in several preclinical and clinical studied due to its ability to activate immune effector cells and trigger anti-tumor immune responses." (PMID 40169985, 2025).
tumor (continued). "Based on this rationale, it has been proposed that neutralization of IL-1α could have the potential to reduce tumour growth and reverse or improve antitumoral immune response in CRC." (PMID 39820336, 2025). "When tumor-bearing mice develop LC, the lesions themselves become a source of IL-1α and IL-1β." (PMID 41179937, 2025). "Yet, 4T1 IL-1α KO cells evoke a much stronger anti-tumor immune response in an immune-competent host, which compensates for the increase in cell malignancy and suppresses tumor growth." (PMID 38612760, 2024). "Among the potential candidates, we postulated that exposure to cell debris could instigate the production of IL-1α by MPs in lung tumors, given the cellular turnover of tumor cells that occurs in the local microenvironment." (PMID 39236155, 2024). "Tumor-released IL-1α promoted tumor development by recruiting MDSCs to inhibit T cell activation." (PMID 38520006, 2024). "Tumour cell-derived IL-1α is a major inducer of Tregs that attracts the chemokine CCL22, and therapeutic blockade of the IL-1 pathway may also be an effective approach to limiting tumour-induced immunosuppression." (PMID 38475858, 2024). "Moreover, the expression of TSLP by myeloid cells (neutrophils and monocytes), induced by tumor-derived IL-1α, favored tumor cells survival." (PMID 38557942, 2024). "Il1α, Ccl2, Cxcl5, and Cxcl10 were significantly downregulated in Ifi35ko 4T1 tumor cells." (PMID 38216673, 2024). "Importantly, we also observed that exposing these cells to apoptotic tumor cell debris elicited a much stronger IL-1α response from old monocytes than from young monocytes." (PMID 39236155, 2024). "Our results also show reduced expression of chemokines in 4T1 IL-1α KO cells, which could potentially lead to a diminished recruitment of immune cells to the tumor." (PMID 38612760, 2024). "Based on this observation, we surmised that the IL-1α produced by local MPs found in tumor lesions may fuel enhanced emergency myelopoiesis in old mice by promoting a pro-myeloid feedback loop with HSPCs in bone marrow." (PMID 39236155, 2024). "In addition, studies has shown that IL-1α and IL-1β act as tumor-specific Th1 mediators in the fight against cancer." (PMID 38745115, 2024). "Additionally, IL1A-NF-κB signaling induces the secretion of pro-inflammatory cytokines and chemokines, creating a tumor-promoting microenvironment." (PMID 39065771, 2024). "We observed that Il1a-/- mice with a young immune system exhibited significantly reduced tumor burden, compared to WT recipients, but notably, we discovered that genetically deleting IL-1α from non-immune cells does not impact lung tumor growth in the presence of an aged immune system." (PMID 39236155, 2024). "In fact, cells deficient in IL-1α that were injected into IL-1α KO mice did not grow at all, while tumor development induced by 4T1/WT cells was strongly suppressed." (PMID 38612760, 2024). "Moreover, IL-1α promotes the development of diverse chronic inflammatory diseases and is tightly involved in tumor development." (PMID 38612760, 2024). "In tumor tissues, IL-1α, IL-1β, IL1R1, IL1RL1, IL1F10, IL33, CASP1, and AIM2 are highly expressed." (PMID 39461030, 2024). "In fact, CTL infiltration foci could be detected in 4T1 IL-1α KO-derived tumors already on day 4 after tumor cell injection." (PMID 38612760, 2024). "Therefore, IL1A’s involvement in HNSCC pathogenesis highlights its potential as a therapeutic target for inhibiting tumor progression and improving patient outcomes." (PMID 39065771, 2024). "Recently, a paper revealed that the tumor response to cetuximab could be enhanced by increasing the levels of IL-1α." (PMID 37741993, 2023). "Therefore, reduction in tumor-promoting TAMs alone cannot offset the combined detrimental effects of lymphoid and IFN loss in Il1a–/–;Il1b–/–;Ntv-a mice." (PMID 37733448, 2023).
tumor (continued). "Then, to investigate whether macrophages were recruited in TME by A549S25E cells showing high expression of VEGFA and IL1A, mouse tumor tissues were stained with specific macrophage antibodies for TAM marker CD163 and pan-macrophage marker CD68." (PMID 37968723, 2023). "Second, IL-1α released by the tumor cells acts distally to induce TNFα expression in HSPCs." (PMID 37134077, 2023). "For instance, tumor cells could release IL-1α during the necroptosis process to activate dendritic cells (DCs)." (PMID 37169000, 2023). "In addition, IL-1α mediates paracrine senescence in neighboring cells to suppress tumor progression, and IL-1α, IL-6, and IL-8 mediate the recruitment of M1-like macrophages, T helper 1 cells, and NKs to the TME." (PMID 36945046, 2023). "We propose that polymeric microparticle (MP)‐based delivery of IL‐1α will suppress the acute pro‐inflammatory side effects by allowing for slow and controlled release of IL‐1α systemically, while simultaneously triggering an anti‐tumor immune response." (PMID 37206237, 2023). "The reason was that necrotic tumor cells could release IL-1α to activate dendritic cells (DCs) which could induce an anti-tumor immune response by producing cytotoxic IL-12 or activating CD8+ T cells." (PMID 38130918, 2023). "Given the role of IL1R1 in tumor progression, our findings suggest that preventing the binding of IL1α and its receptor by using antibodies against IL1α or IL1R1 could be new therapeutic strategies to reduce malignancy of TNBC." (PMID 37551997, 2023). "Both the tumor-suppressive and tumor-promoting functions of IL-1α on tumors have been demonstrated." (PMID 37998338, 2023). "Furthermore, experimental observation demonstrated that the overexpression of IL-1RA in IL-1α expressing Kyse-410 EC cells decreased tumor cell proliferation and reduced expression of VEGF-A, a potent angiogenesis inducer." (PMID 37046658, 2023). "Furthermore, there is a marked reduction in the expression of IL-1α and IL-1β in the tumor tissues of Anakinra treated mice compared to control groups." (PMID 38152619, 2023). "However, genetic deletion of both IL-1α and IL-1β results in decreased recruitment of lymphoid cells and loss of IFN signaling in immune cells, allowing the tumor to escape immune control and worsen survival." (PMID 37733448, 2023). "Similarly, IL-1A can also promote macrophage aggregation to stimulate angiogenesis, leading to the progression and metastasis of tumor." (PMID 38111060, 2023). "Our analysis of correlations between FOX gene expression and IL-1α or IL6 revealed 10 members that might be involved in tumor senescence." (PMID 36622275, 2023). "We showed that direct contact with tumor cells, TGFβ, IL1α or cytostatic drugs induced activation of CAFs that correlated with the expression of satDNA and the formation of a secretory senescence phenotype which was reduced by knock-down of satellite RNAs (graphical abstract)." (PMID 36635266, 2023). "As an important participant in tumor progression, IL-1α could also have multiple source and effector cells in TME68." (PMID 37524695, 2023). "Furthermore, they have previously shown tumor cell-derived IL1α induces stromal-derived IL-6, reciprocally activating tumor cell-autonomous STAT3 signaling, a well-known indicator of chemoresistance and oncogenic signaling in PDAC." (PMID 36902166, 2023). "Unfortunately, the use of IL‐1α or IL‐1β as anti‐cancer agents in clinical trials have not lived up to the initial excitement caused by the observed preclinical anti‐tumor immune responses." (PMID 37206237, 2023). "In NSCLC, BRAFV600E promotes the generation of interleukin (IL), such as IL-1α and IL-1β, hence repressing the recognition and killing capacity of tumor-specific CTLs, partially through the upregulation of PD-1 ligands, PD-L1, and PD-L2, and via secretion of cyclooxygenase (COX-2)." (PMID 37345046, 2023). "This study shows that tumor-produced IL-1α and LIF promote extramedullary hematopoiesis." (PMID 37134077, 2023).
tumor (continued). "IL-1α, IL-6, and IL-8 can promote immune processes involving the killing of tumor-related cells and induce apoptosis, which has the effect of directly inhibiting and killing tumor cells." (PMID 35855902, 2022). "It is reported that CARD9 is highly expressed in the infiltrated macrophages during carcinoma progression with enhanced production of tumor-promoting cytokines (IL-10 and IL-1α), and decreased production of anti-tumor cytokine IL-12, thus, contributing to tumor metastasis." (PMID 35432375, 2022). "Subsequently, we analyzed SQLE expression and its association with biomarkers of MHC (B2M, HLA-B, HLA-C, TAP1, and TAP2), dendritic cells (BATF3), macrophages (CD68 and IL1A), type-I anti-tumor responses (CD8A and GZMB), and cell proliferation (MKI67) in 178 PAAD tissues." (PMID 35720314, 2022). "In vivo, a dose of 3 μg nanobody per gram of body weight in tumor‐bearing mice could attenuate tumor progression and suppress excessive circulating levels of IL‐1a, IL‐2, IL‐10, IL‐12, and IL‐17A pro‐inflammatory cytokines." (PMID 34694686, 2022). "The increase in IL-1a in the healthy hemisphere by the 21st day detected in our study correlates with tumor regrowth and might be related to the inflammatory response affecting the entire brain as the tumor grows." (PMID 35884700, 2022). "Both IL-1α and IL-1β stimulated tumor-induced osteoclastogenesis." (PMID 36614130, 2022). "In addition, tumor-derived interleukin 1 alpha (IL1A) induces LIF upregulation in PSCs, leading to the activation of JAK-STAT signaling pathways to promote iCAF induction." (PMID 35805064, 2022). "IL-1α could also suppress the progression of the tumor by inducing G0-G1 phase cell cycle arrest in PCa." (PMID 36237303, 2022). "Likewise, oral administration of β-1,3-Glucan derived from yeast (Saccharomyces cerevisae) in tumor-bearing mice stimulates granulocyte-macrophage progenitors and active cytokines such as IFN-γ, IL-1α, and IL-6, suppressing tumor progression." (PMID 35401838, 2022). "Interestingly, CD105pos and CD105neg subpopulations of normal pancreatic fibroblasts were also isolated which retained their CD105 status even after co-culture with a tumour cell-conditioned medium or with fibroblast-modulating signals (TGFβ1, Il1a and IFNγ)." (PMID 36358721, 2022). "Of immediate interest was IL-1α, a cytokine that induces COX-2 in tumor-associated fibroblasts." (PMID 36426368, 2022). "Targeting neutrophil or inflammatory cytokines IL-1A and IL-6 could be potential therapies to restore anti-tumor immune reaction in PCPs." (PMID 36389809, 2022). "IL-1α could activate NFκB–regulated genes coding for proteins contributing to the tumor inflammatory microenvironment." (PMID 36012769, 2022). "In serum of CT26 tumor-bearing mice, there was extensive overlap with the factors detected in CT26-conditioned media: following mediators identified in conditioned media showed at least a 1.2-fold increase in CT26 tumor-bearing mice: IL-1α, IL-2, IL-13, CCL2/5/19, LIX, CX3CL1, CXCL1/2/10 and CCL19." (PMID 35962398, 2022). "In addition, CCL22 can also be induced in tumor infiltrating immune cells by interleukin-1 (IL-1α) derived from cancer cells." (PMID 35176085, 2022). "Analysis of flash-frozen whole-tumour lysate revealed substantial levels of IL-1α, IL-1β and IL-18." (PMID 35545675, 2022). "The stromal paracrine secretion of SOD3 then continues to support the proliferation of tumor cells, and, correspondingly, reduces the affinity of tumor cells to tumor stroma by decreasing the expression of chemotactic cytokines, such as IL1α and MCP-1, in the stromal compartment." (PMID 36077709, 2022). "In addition, pro-inflammatory cytokines, IL-1α released by necroptotic cells, can also recruit inflammatory cells and incur inflammation, which can stimulate the proliferation of tumor cells and potentially facilitate neoplastic progression." (PMID 36361505, 2022).